DHRS4 (dehydrogenase/reductase 4)
Description:
NADPH-dependent oxidoreductase which catalyzes the reduction of a variety of compounds bearing carbonyl groups including ketosteroids, alpha-dicarbonyl compounds, aldehydes, aromatic ketones and quinones. Reduces 3-ketosteroids and benzil into 3beta-hydroxysteroids and R-benzoin, respectively, in contrast to the stereoselectivity of non-primate DHRS4s which produce 3alpha-hydroxysteroids and S-benzoin. Displays low activity toward all-trans-retinal and no activity toward 9-cis-retinal as compared to non-primate mammals. In the reverse reaction, catalyze the NAD-dependent oxidation of 3beta-hydroxysteroids and alcohol, but with much lower efficiency. Involved in the metabolism of 3beta-hydroxysteroids, isatin and xenobiotic carbonyl compounds. [Isoform 7]: No detected catalytic activity in vitro, possibly due to the lack of catalytic site. [Isoform 8]: NADPH-dependent oxidoreductase which catalyzes the reduction of a variety of compounds bearing carbonyl groups including ketosteroids, alpha-dicarbonyl compounds, aldehydes, aromatic ketones and quinones. Involved in the metabolism of 3beta-hydroxysteroids, isatin and xenobiotic carbonyl compounds. Has a higher catalytic activity for xenobiotic alpha-dicarbonyl compounds, sucha as benzil, than isoform 1 and is involved in benzil detoxification.
Synonyms: CR; NRDR; humNRDR; PSCD; SDR25C2; SCAD-SRL; SDR-SRL; FLJ11008; PHCR; SDR25C1
Tractability: Small molecule: a structure with a bound ligand is known; it has a binding pocket of medium quality. PROTAC: ubiquitination databases record sites on it; its protein half-life has been measured.
Gene: Protein-coding gene on chromosome 14 (23,953,713 to 23,969,279, forward strand). Ensembl gene ENSG00000157326.
Subcellular location: Peroxisome (Isoform 1); Nucleus (Isoform 7)
Subcellular location (Human Protein Atlas): Vesicles; Nuclear membrane
Pathways (Reactome):
Protein localization: Peroxisomal protein import
Signal Transduction: RA biosynthesis pathway
Gene Ontology:
Molecular function: 3-beta-hydroxy-5-beta-steroid dehydrogenase (NADP+) activity; 3-beta-hydroxysteroid 3-dehydrogenase (NADP+) activity; alcohol dehydrogenase [NAD(P)+] activity; carbonyl reductase (NADPH) activity; identical protein binding; oxidoreductase activity, acting on NAD(P)H, quinone or similar compound as acceptor; all-trans-retinol dehydrogenase (NADP+) activity
Biological process: alcohol metabolic process; ketone metabolic process; positive regulation of reactive oxygen species metabolic process; steroid metabolic process; retinal metabolic process; retinol metabolic process
Cellular component: mitochondrion; nucleus; peroxisomal membrane; peroxisome; cytosol; endoplasmic reticulum membrane; peroxisomal matrix
Genetic constraint (gnomAD): Loss-of-function variants: 20 observed, 27.85 expected, observed/expected ratio (o/e) 0.72, 90% interval 0.5 to 1.04. The upper end of that interval is the gene's LOEUF score, 1.04, which puts it in group 4 of 6, group 1 being the genes least tolerant of losing a copy. Missense variants: 378 observed, 360.72 expected, observed/expected ratio (o/e) 1.05, 90% interval 0.96 to 1.14. Synonymous variants: 144 observed, 147.34 expected, observed/expected ratio (o/e) 0.98, 90% interval 0.85 to 1.12.
Homologues: Orthologues: chimpanzee DHRS4 (98% identical), macaque DHRS4 (96% identical), dog DHRS4 (85% identical), rabbit DHRS4 (83% identical), guinea pig DHRS4 (83% identical), mouse Dhrs4 (81% identical), rat Dhrs4 (80% identical), pig DHRS4 (68% identical), zebrafish zgc:101858 (25% identical), tropical clawed frog MGC79752 (24% identical), Drosophila melanogaster CG3699 (23% identical), Caenorhabditis elegans Y47G6A.22 (23% identical), and 20 more. Paralogues in human: DHRS4L2 (72% identical), DHRS2 (60% identical), CBR1 (24% identical), RDH8 (24% identical), HSD11B1 (23% identical), CBR3 (22% identical), DHRS7 (22% identical), DHRS7B (22% identical), DHRS11 (21% identical), DHRS7C (20% identical), HSD11B1L (20% identical), DHRS1 (18% identical), and 1 more.
Diseases named in the same sentence as DHRS4 in open-access papers:
DHRS4 is named in the same sentence as 19 diseases in open-access papers, as found by Europe PMC text mining. Sharing a sentence is not in itself a finding about the gene and the disease. The quoted sentences say what the papers report.
breast carcinoma (3 papers, 2019 to 2025). "The same phenomenon may be occurring in our breast cancer model leading to the hypomethylated state of the DHRS4 promoter." (PMID 32051475, 2020).
glioma (3 papers, 2020 to 2025). A benign or malignant brain and spinal cord tumor that arises from glial cells (astrocytes, oligodendrocytes, ependymal cells). "Simultaneously, we observed that the knockdown of DHRS4 rescued the downregulation of glioma proliferation, invasion, and migration caused by treatment with a mir-29a-5p inhibitor." (PMID 33014873, 2020). "Taken together, these findings provide insights into the mechanisms underlying the effect of miR-29a-5p on suppressing glioma progression, and DHRS4 may be directly involved as a potential cancer-promoting molecule." (PMID 33014873, 2020). "Taken together, the results demonstrated that DHRS4 is a direct target of miR-29a-5p in glioma cells and negatively correlates with miR-29a-5p." (PMID 33014873, 2020). "On the basis of bioinformatics, dehydrogenase/reductase 4 (DHRS4) was considered a potential target of miR-29a-5p and was also found to be highly expressed in gliomas in our experiments." (PMID 33014873, 2020). "DHRS4 was selected for further study because it is highly expressed in glioma, according to GEPIA software." (PMID 33014873, 2020). "Having established that si-DHRS4 inhibits glioma cell proliferation, invasion, and migration in vitro, we evaluated the growth promoting effect of DHRS4 in vivo using a subcutaneous tumorigenesis experiment." (PMID 33014873, 2020). "Our further investigations showed that knockdown of DHRS4 inhibited the proliferation, migration, and invasion of glioma cells in vitro." (PMID 33014873, 2020). "In summary, the results indicate that overexpression of miR-29a-5p suppresses glioma cell proliferation, invasion, and migration by directly targeting DHRS4." (PMID 33014873, 2020). "The expression level of DHRS4 was also significantly up-regulated in the high-grade glioma tissues compared with normal brain tissues and low-grade glioma tissues, on the basis of immunohistochemical staining (p < 0.001)." (PMID 33014873, 2020). "However, the detailed role and mechanism by which DHRS4 promotes glioma development and progression should be investigated in future work." (PMID 33014873, 2020). "The present findings demonstrate that miR-29a-5p suppresses cell proliferation, invasion, and migration by targeting DHRS4, and DHRS4 may be a potential new oncogene and prognostic factor in gliomas." (PMID 33014873, 2020). "Moreover, with a luciferase reporter assay, DHRS4 was found to be a target gene of miR-29a-5p and to be correlated with glioma proliferation, invasion, and migration in our in vivo and in vitro experiments." (PMID 33014873, 2020). "Furthermore, we clarified the role of DHRS4 in glioma through in vitro and in vivo experiments." (PMID 33014873, 2020). "Furthermore, DHRS4 is considered an oncogene and has significant value as an unfavorable indicator for glioma patients, and it may serve as a therapeutic target in the future." (PMID 33014873, 2020).
cancer (5 papers, 2016 to 2025). A tumor composed of atypical neoplastic, often pleomorphic cells that invade other tissues. "The DHRS4 gene cluster is located in an area of segmental duplications, and its expression is downregulated in certain human cancers." (PMID 33014873, 2020).
tumor (2 papers, 2024 to 2025). "The results showed that compared with normal tissues, the mRNA expression of five genes, ACBD5, ATAD1, DHRS4, GRHPR, and IDH1, was significantly up-regulated in tumor tissues." (PMID 38406287, 2024).
DHRS4 also shares sentences with these, for which no sentence is quoted: infection (5 papers); bacterial infection (2); cervical cancer (2); clear cell renal carcinoma (2); Alzheimer disease (1); amyotrophic lateral sclerosis (1); blood disease (1); endometrial carcinoma (1); gastroenteritis (1); kidney cancer (1); leishmaniasis (1); lung carcinoma (1); mucinous tumors (1); neuroblastoma (1); virus infection (1).